SRSF3P1 (SRSF3 pseudogene 1)
Gene: Processed pseudogene on chromosome 11 (18,665,050 to 18,665,548, forward strand). Ensembl gene ENSG00000257043.
Diseases named in the same sentence as SRSF3P1 in open-access papers:
SRSF3P1 is named in the same sentence as 1 disease in open-access papers, as found by Europe PMC text mining. Sharing a sentence is not in itself a finding about the gene and the disease. The quoted sentences say what the papers report.
breast carcinoma (1 paper, 2023). "Two intronic AIMs (rs13267382: chr8, LINC00536; rs9952980: chr18, SLC14A2) and two intergenic AIMs (rs10832963: chr11, SPTY2D1 - SRSF3P1; rs11814448: chr10) were also found to be associated with breast cancer in samples of European and Asian ancestry." (PMID 36911410, 2023).